NANOGP8 (Nanog homeobox retrogene P8)
Description:
May act as a transcription regulator (By similarity). When overexpressed, promotes entry of cells into S phase and cell proliferation.
Synonyms: PN8
Tractability: No criterion of Open Targets' tractability assessment is met for any kind of drug.
Gene: Protein-coding gene on chromosome 15 (35,083,410 to 35,085,295, reverse strand). Ensembl gene ENSG00000255192.
Subcellular location: Nucleus
Subcellular location (Human Protein Atlas): Nucleoplasm; Vesicles
Gene Ontology:
Molecular function: DNA-binding transcription factor activity, RNA polymerase II-specific; RNA polymerase II cis-regulatory region sequence-specific DNA binding; DNA binding
Biological process: positive regulation of cell cycle G1/S phase transition; positive regulation of cell population proliferation; cell differentiation; regulation of transcription by RNA polymerase II; stem cell population maintenance; regulation of DNA-templated transcription
Cellular component: nucleoplasm; nucleus
Genetic constraint (gnomAD): Missense variants: 190 observed, 281.7 expected, observed/expected ratio (o/e) 0.67, 90% interval 0.6 to 0.76. Synonymous variants: 79 observed, 98.09 expected, observed/expected ratio (o/e) 0.81, 90% interval 0.67 to 0.97.
Homologues: Orthologues: chimpanzee NANOG (98% identical), macaque NANOG (94% identical), pig NANOG (75% identical), dog NANOG (68% identical), rat Nanog (62% identical), mouse Nanog (56% identical), zebrafish nanog (22% identical), Caenorhabditis elegans ceh-43 (17% identical), Drosophila melanogaster Dll (16% identical). Paralogues in human: NANOG (99% identical), DLX5 (19% identical), DLX3 (18% identical), DLX6 (18% identical), DLX1 (18% identical), DLX4 (17% identical), DLX2 (16% identical), VENTX (15% identical), BSX (14% identical).
Diseases named in the same sentence as NANOGP8 in open-access papers:
NANOGP8 is named in the same sentence as 16 diseases in open-access papers, as found by Europe PMC text mining. Sharing a sentence is not in itself a finding about the gene and the disease. The quoted sentences say what the papers report.
gastric cancer (7 papers, 2016 to 2024). A primary or metastatic malignant neoplasm involving the stomach. "The homology cassette transcription factor NANOG is essential for embryonic stem cell renewal, and the related pseudogene NANOGP8 is a major contributor to NANOG-induced effects on gastric cancer." (PMID 38952556, 2024). "It was recently shown that ectopic expression of the embryonic stem cells transcription factor, NANOGP8, in gastric cancer cells, promotes sphere formation and chemo-resistance by up-regulating EMT inducers and CSCs markers." (PMID 37773114, 2023). "NANOGP8 expression was significantly elevated in gastric cancer and knockdown of NANOGP8 resulted in decreased proliferation and promoted apoptosis of gastric cancer cells." (PMID 32185172, 2020). "Since we observed that NANOGP8 expression is up-regulated in sphere-forming cells, then we ask if NANOGP8 has an impact on EMT property for gastric cancer cells." (PMID 29689047, 2018). "It is believed that EMT is coupled with cancer stem cell, therefore, we asked if NANOGP8 regulates putative gastric cancer stem cell markers." (PMID 29689047, 2018). "To explore if NANOGP8 influence drug sensitivity in gastric cancer cells, we examined drug sensitivity in NANOGP8 transfected and mock cells at different L-OHP concentration (15uM/L, 30uM/L, 60uM/L, 100uM/L) using an MTT assay." (PMID 29689047, 2018). "NANOGP8 is mainly responsible for NANOG expression in sphere-forming (stem cell-like) cells derived from gastric cancer cell lines regardless their differentiation status." (PMID 29689047, 2018). "The results clearly show that NANOGP8 plays a key role in gastric cancer initiation, progression and malignancy, strongly suggests NANOGP8 is an excellent therapeutic target." (PMID 29689047, 2018). "NANOGP8 is correlated with cell proliferation, migration, invasion, clonogenic capacity, β-catenin accumulation in nucleus, and chemoresistance in gastric cancer." (PMID 29689047, 2018). "To visualize the localization of NANOGP8 and Lgr5 in gastric cancer sphere-forming cells and adherent cells, we performed immunofluorescence double staining with NANOGP8 and Lgr5 specific monoclonal antibodies." (PMID 29689047, 2018). "The difference is extremely significant (P<0.01), indicating NANOGP8 over-expression can promote sphere-forming capacity for gastric cancer cell line." (PMID 29689047, 2018). "This is the first systematic study to show that NANOGP8, a human unique retrogene, is the key gene to determine gastric cancer malignancy." (PMID 29689047, 2018). "Additionally, the expression of NANOGP8 has been found to promote cell migration and proliferation in gastric cancer cells." (PMID 37372456, 2023). "In gastric cancer, NANOGP8 overexpression leads to anti-oxaliplatin (L-OHP) resistance." (PMID 32226927, 2020). "We chose a set of genes that were reported to encode gastric cancer stem cell markers such as LGR5, CD133, CD44, CD54, ABCG2 and MSI1, and then performed qPCR to detect their expression in both NANOGP8-transfected (SGC7901-NANOGP8) and mock cells (SGC7901-NC)." (PMID 29689047, 2018). "Experiments of cell proliferation, migration, invasion, clonogenic assay, sphere cell growth assays, cell cycle analysis, β-catenin accumulation and translocation in nucleus, and drug resistance were conducted to measure the impact of NANOGP8 on malignant statuses of gastric cancer cells." (PMID 29689047, 2018). "NANOGP8 is a promising molecular target for clinical intervention of gastric cancer." (PMID 29689047, 2018). "The transmembrane cells from NANOGP8-transfected cells are significantly more than mock control cells (746±12 vs. 412±13) with an 81.07% of increase (P<0.01), which indicate that NANOGP8 over-expression promote invasion potential for gastric cancer cell line SGC7901." (PMID 29689047, 2018).
gastric cancer (continued). "Ectopic expression of NANOGP8 up-regulates CSC markers and EMT signature genes in gastric cancer cells, which, in turn, greatly enhance cell proliferation, migration, invasion, sphere cell growth, Wnt signaling and chemoresistance." (PMID 29689047, 2018). "Our systematic study clearly demonstrated that NANOGP8 is the essential regulator of stemness, EMT and β-catenin in gastric CSC, thereby responsible for gastric cancer malignancy and drug resistance." (PMID 29689047, 2018). "Because NANOGP8 promotes LGR5 expression the most significantly, and LGR5 is reported to be gastric cancer stem cell marker and one of the Wnt receptors, therefore, we want to explore if NANOGP8 can enhance Wnt signal transduction." (PMID 29689047, 2018). "The protein expression was analyzed by Western blot that was consistent with qPCR, suggesting NANOGP8 may be a major regulator for EMT and CSC in gastric cancer cells." (PMID 29689047, 2018).
glioblastoma (4 papers, 2018 to 2023). The most malignant astrocytic tumor (WHO grade IV). "In our previously published study, we have reported that differential sequences found in pseudo/retro-oncogene NANOGP8 can be used as potential diagnostic biomarker for Glioblastoma multiforme (GBM)." (PMID 32092088, 2020). "Recently, researchers have shown increased expression levels of NANOGP8 in glioblastoma cancer stem cells and have suggested that NANOGP8 may participate in the reprogramming of normal cells into cancerous states." (PMID 29787607, 2018). "However, in this study, we evaluated NANOGP8 expression in glioblastoma multiforme (GBM) tissue from a surgically removed brain tumor of a patient." (PMID 36696426, 2023).
breast cancer (3 papers, 2013 to 2017). A primary or metastatic malignant neoplasm involving the breast. "NANOGP8 overexpression in vitro promotes sphere formation and migration in a prostate cancer cell line and drug resistance in a breast cancer cell line." (PMID 26087476, 2015). "NANOGP8 has been recognized as a retrogene and was recently found to be expressed in various cancer tissues and several cancer cell lines including breast cancer MCF-7 cells." (PMID 23662114, 2013). "A recent study demonstrated that NanogP8 expression alone in the mammary tissue is incapable of inducing mammary tumors but could enhance mammary tumorigenesis and accelerate metastasis of Wnt-1 transgenic mice." (PMID 28881767, 2017). "This conclusion is consistent with two other studies showing that NanogP8 overexpression alone in transgenic animals is unable to initiate mammary tumor development or Nanog only weakly enhances liver tumorigenesis in a hepatocellular carcinoma reconstitution model." (PMID 28881767, 2017).
colon cancer (3 papers, 2017 to 2025). "NAT10 can increase NANOGP8 ac4C modification levels and support NANOGP8 mRNA stability in colon cancer to maintain stemness and resist chemotherapy." (PMID 41316475, 2025). "Our work has shown that shRNA-mediated knockdown of NanogP8 in prostate, breast, and colon cancer cells inhibits tumor regeneration whereas inducible overexpression of NanogP8 promotes cancer stem cell phenotypes and properties." (PMID 28881767, 2017). "In addition, NAT10 was shown to promote the maintenance of stemness among colon cancer cells and enhance chemical resistance by stabilizing NANOGP8 mRNA." (PMID 40606759, 2025). "Our lab has shown that various cancer cells preferentially express NanogP8 mRNA, primary PCa samples contain more Nanog protein-expressing cells than the matched benign tissues, and down-regulation of endogenous Nanog inhibits tumor regeneration in prostate, breast and colon cancer cells." (PMID 28881767, 2017).
colorectal cancer (3 papers, 2017 to 2022). A primary or metastatic malignant neoplasm that affects the colon or rectum. "It has been reported that liver parenchymal endothelial cells can mediate the initiation of CSCs in colorectal cancer (CRC) in a paracrine manner by activating the Nanog homeobox retrogene P8 (NANOGP8) pathway." (PMID 33898430, 2021).
prostate carcinoma (3 papers, 2015 to 2022). A carcinoma that arises from epithelial cells of the prostate gland. "Our results indicate that NANOG1 and NANOGP8 are expressed equally and that both genes activate many properties that are associated with the malignant potential in prostate cancer cells, including sphere formation capacity, migration capability, drug resistance, and tumorigenic potential." (PMID 26087476, 2015). "In summary, we established NANOG1- and NANOGP8-knockout prostate cancer cell lines using the CRISPR/Cas9 system." (PMID 26087476, 2015). "We established NANOG- and NANOGP8-knockout DU145 prostate cancer cell lines using the CRISPR/Cas9 system." (PMID 26087476, 2015). "Our results indicate that NANOG1 and NANOGP8 are involved in the tumorigenic potential of prostate cancer cells, which is consistent with these previous studies." (PMID 26087476, 2015). "Therefore, wound-healing assays were performed to examine the effect of NANOG1 and NANOGP8 on prostate cancer cell migration." (PMID 26087476, 2015). "In the DU145 prostate cancer cell line with endogenous NANOG1 and NANOGP8 proteins, both NANOG1 and NANOGP8 contributed equally to many properties associated with malignant potential in prostate cancer, including sphere formation, migration, drug resistance, and tumorigenic potential." (PMID 26087476, 2015). "Therefore, we hypothesize that NANOG1 and NANOGP8 reciprocally promote each other's expression in prostate cancer cells." (PMID 26087476, 2015). "Nanog has shown to be predominantly expressed from the NanogP8 pseudogene in a panel of prostate carcinoma cells including DU145, LNCaP, and PC-3 and primary prostate carcinoma cells." (PMID 35800367, 2022). "Our results revealed an equivalent proportion of NANOG1 and NANOGP8 protein expression and an equivalent function of NANOG1 and NANOGP8 genes in the regulation of the malignant potential of DU145 prostate cancer cells." (PMID 26087476, 2015). "This study used the CRISPR/Cas9 system to establish NANOG1- and NANOGP8-knockout prostate cancer cell lines and examine the function of NANOG1 and NANOGP8 genes in prostate cancer cells." (PMID 26087476, 2015). "This study established NANOG1- and NANOGP8-knockout, DU145 prostate cancer cell lines using CRISPR/Cas9 system-mediated genetic engineering." (PMID 26087476, 2015). "Therefore, NANOGP8 is likely a primary contributor of NANOG protein expression in various somatic cancers, including prostate cancer." (PMID 26087476, 2015).
colorectal tumor (2 papers, 2017 to 2024). "Studies showed that normal colon mucosa has low or undetectable NANOG and NANOGP8, whereas colorectal tumor tissues and cancer cells have elevated NANOGP8 expression with no changes in NANOG." (PMID 28453235, 2017).
prostate tumor (2 papers, 2014 to 2017). "Our results indicate that overexpression of NanogP8 alone in prostate luminal cells is unable to initiate mouse prostate tumor development in both androgen intact and androgen-deficient conditions, although NanogP8 expression appears to slightly promote prostate tumorigenesis in ARR2PB-Myc mice." (PMID 28881767, 2017). "Our sequencing analyses reveal that embryonal carcinoma (EC) NTERA-2 cells express Nanog1 but not NanogP8 mRNA whereas all somatic cancer cells (6 different types including primary prostate tumor-derived cells) show 5 of the 6 nt differences specific to NanogP8." (PMID 24598770, 2014). "Indeed, our own sequencing and differential qRT-PCR analysis has demonstrated that the Nanog mRNA in multiple somatic cancer cell types (including primary prostate tumors) is derived from the NanogP8 locus." (PMID 24598770, 2014). "We have shown that enforced expression of NanogP8 promotes prostate CSC characteristics and, in xenograft mouse models, NanogP8 overexpression promotes prostate tumor growth in castrated conditions." (PMID 28881767, 2017).
cancer (21 papers, 2012 to 2024). A tumor composed of atypical neoplastic, often pleomorphic cells that invade other tissues. "To explore if NANOGP8 expression is associated with enhanced cancer cell migration, we performed wound-healing assays in SGC7901 cell line after NANOGP8 transfection." (PMID 29689047, 2018). "Some variants between the reference sequences of NANOG and NANOGP8 utilized in cancer research to distinguish RT-PCR products are polymorphic within NANOG or NANOGP8 and thus are not universally reliable as distinguishing features." (PMID 23173096, 2012). "NANOGP8 is a human-specific retrogene and it has been proposed that its expression in cancers could explain higher the predisposition to cancers in humans than other primates." (PMID 32580970, 2020). "The critical roles of NANOG and NANOGP8 in cancer progression leads the association of these genes with exosomes to be significant, and may allow for exosomal NANOG to function as a powerful diagnostic biomarker." (PMID 29787607, 2018). "The fact that NANOGP8 is a human-specific retro-oncogene may partially explain the higher genetic predisposition for cancer in humans compared with other primates." (PMID 23173096, 2012). "Finally, the recent evolution of NANOGP8 exclusively in the human ancestral lineage may partially explain some uniquely human aspects of cancer, including the higher predisposition for cancer in humans compared with other primates." (PMID 23173096, 2012). "Among other molecules transported within EV cargo, NANOGP8 has been suggested as an important promoter of cancer stemness in different malignancies, GB included." (PMID 39473666, 2024). "For instance, glioblastoma EVs carrying NANOGP8 DNA promotor sequence and transcriptional regulatory components can mediate transformation from normal or cancer cells to cancer stem cells." (PMID 39266560, 2024). "Because more of the 22mer insert was found in NANOGP8 3′-DNA in cancer cell-secreted exosomes, we wanted to check the exosome-localization capability of the insert alone." (PMID 39000405, 2024). "The role of various cancer-specific TFs for which the TFBS are detected in exosomal NANOGP8 DNA should also be analyzed." (PMID 36696426, 2023). "In the context of GBM, transcriptional activation of NANOGP8 confers stemness to cancer cells and affects the downstream genes, e.g. ABCG2, a multigene drug transporter gene responsible for drug efflux." (PMID 36696426, 2023). "Significantly higher NANOGP8 transcription was observed in GBM cancer stem cells (CSCs) than in GBM cancer cells or neural stem cells (NSCs), despite identical sequences of NANOGP8-upstream genomic region in all the cell lines." (PMID 36696426, 2023). "In our experiments, CSCs show higher MGMT expression along with significant elevation of cancer stemness marker NANOGP8 as compared to GBM." (PMID 36834653, 2023). "Our recent discoveries have revealed the presence of NANOGP8 in the exosomes released by cancer cells." (PMID 37372456, 2023). "We have previously reported that cancer cell originated exosomes, including GBM, have NANOG and NANOGP8 DNA associated with them." (PMID 32092088, 2020). "Occurrence of the insert in 3′ UTR region of NANOGP8 is compelling and implies the possibility of its role in translational modification of cancer." (PMID 33137926, 2020). "Although to a much lower extent than regular NANOG, expression of the human-specific NANOGP8 retrogene, often expressed in human cancers, was also slightly induced by the reprograming process in a STAT3-dependent manner." (PMID 32580970, 2020). "Several studies investigating which NANOGs were expressed in cancer cells and tissues identified that NANOGP8 was the most prevalent NANOG expressed in many human cancers and contributed to their ‘stemness’ and proliferative capacity." (PMID 32580970, 2020). "As we observed, β-catenin is heavily accumulated in nucleus of NANOGP8 over-expressed cancer cells, while it is undetectable in nucleus of the mock cells." (PMID 29689047, 2018).